CD4 (CD4 molecule)
Diseases named in the same sentence as CD4 in open-access papers (continued):
Sharing a sentence is not in itself a finding about the gene and the disease.
tumor (continued). "Regardless, while no significant changes or apparently inconclusive changes (associated to a decrease of CD4+ cells) were observed in our experiments, tumor-infiltrating specific CD4+ and CD8+ T-cell population could be a small fraction of the total T cells." (PMID 31695610, 2019). "These protective effects of subcutaneous RA/CTS polyplex treatment were associated with the highest tumor antigen-specific humoral and cellular immune responses after tumor challenge, and with the greatest infiltration of CD4 helper T cell and CD8 T cell into the tumor tissues." (PMID 31847372, 2019). "Similarly, other reports also showed the induction of predominant CD4+ T cell responses after RNA vaccines targeting tumor-specific mutations in mouse models and humans." (PMID 30813491, 2019). "It has been proposed that the accumulation of Tregs in tumor microenvironments is caused by increases in the recruitment of natural (n)Tregs from peripheral blood and the tumor-cell-mediated induction of (i)Tregs from CD4+CD25−T cells." (PMID 30718502, 2019). "To examine whether the observed difference in tumor growth in vivo was associated with distinct cell infiltrates, we examined fractions of CD4+ and CD8+ T cells, NK cells and T regularity (Treg) cells in shLDH-A deficient and control B16-F10 tumors." (PMID 30934955, 2019). "However, maximum tolerated dose regimens are associated with a loss of CD8+ and CD4+ T-cells and NK cells from the tumor microenvironment, and pro-tumoral activation of cancer-associated fibroblasts." (PMID 31379850, 2019). "ROS not only promote fibrosis by facilitating HSCs activation and migration, but can also directly induce cancer by generating DNA damage and mutations in hepatocytes, or by causing the selective loss of CD4+ T lymphocytes, which mediate tumor immunosurveillance." (PMID 30959975, 2019). "The increase in tumor-associated CD4+ cells following trametinib treatment, raises the possibility that Th1-polarized CD4+ T cells may contribute to the antitumor activity observed." (PMID 30353166, 2019). "CD4+ infiltrates were only associated with tumor shrinkage after therapy when localized at the ITF." (PMID 30717704, 2019). "In addition, the activation and maturation of CD8+ T-cells is also modulated by IFNγ secreted by CD4+ Th1 cells and specific tumor-associated antigens processed by dendritic cells." (PMID 31430935, 2019). "Six immune cells frequently infiltrating tumors were selected, including CD8+ T cells, CD4+ T cells, neutrophils, tumor-associated macrophages (TAMs), natural killer (NK) cells, myeloid-derived suppressor cells (MDSCs), Dendritic cells (DCs), and regulatory T cells (Tregs)." (PMID 31377744, 2019). "Furthermore, we demonstrate that tumor uptake of CD4+ and CD8a+ specific tracers is overall associated with the tumor growth response to Sym021." (PMID 31754392, 2019). "We could speculate that CD4 expression on DP T cells might allow them to respond to MHCII antigens in an effort to overcome resistance mediated by MHCI loss observed in many tumor types." (PMID 30534127, 2018). "Moreover, genetic instability of tumors and constant cell division can result in the loss of tumor antigens recognized by effector T-cells (CD8+ or CD4+ T-cells)." (PMID 29301364, 2018). "Hence, anti-CD4 mAb treatment is associated with an increase in dLN-tumor overlap of the CD8+ T cell repertoire." (PMID 30733724, 2018). "Depletion of CD8+ T cells led to the loss of anti-tumor effects mediated by the combination therapy, whereas depletion of CD4+ T cells led to a decrease in tumor growth compared to mice treated with IL PV-10 in combination with anti-PD-1 antibodies and control NrIgG." (PMID 29694419, 2018). "Researchers further investigated whether the tumor rejection was attributed to ERBB2IP mutation specific CD4+ T cell." (PMID 30473928, 2018).
tumor (continued). "Reduction of several layers of suppression in young tumor-associated CD4+ T cells may help account for the improved tumor response seen in young mice to IL-2/CD40 treatment." (PMID 30560130, 2018). "Moreover, depletion of Treg cells was associated with functional maturation of CD8 and CD4 T cells, as demonstrated by increased interferon γ-producing cells and tumor necrosis factor α-producing T cells within tumor microenvironment but not in the spleen." (PMID 29472691, 2018). "Furthermore, the presence of multiple epitopes restricts the chance of tumor escape by antigen loss while promoting a polyclonal CD4+ and CD8+-dependent T cell responses." (PMID 30477198, 2018). "Furthermore, the existence of Th17 within the tumor microenvironment is associated with the inhibition of INF-γ producing CD4+ cell." (PMID 29662489, 2018). "Foxp3 is a marker of CD4+ immunosuppressive Treg cells, which could suppress an anti-cancer immune response and are associated with tumour progression." (PMID 30559928, 2018). "However, chemokines can recruit CD4+ Th2 cells and CD4+ T regulatory (Treg) cells into the tumor microenvironment, causing inhibited CTL antitumor responses." (PMID 30115834, 2018). "This therapeutic potential was translated to the clinical setting, as adoptive transfer of autologous tumor mutation-specific Th1 CD4 T cells from a patient with metastatic cholangiocarcinoma was able to induce tumor regression upon original administration as well as after tumor recurrence." (PMID 29487705, 2018). "For example, higher frequencies of CD8 tumor infiltrating T cells are associated with improved clinical outcome and survival, but the presence of T regulatory cells (CD4+ FoxP3+) in tumor tissues is associated with reduced survival and high death hazard in patients with ovarian carcinoma." (PMID 29968076, 2018). "The cytotoxic T lymphocytes (CTLs, also CD8+ T cells, marked as CD3+CD8+ T cells) are pivotal immune cells directed against tumor cells susceptible to cell lysis, but CD4+Foxp3+ regulatory T cells (Treg) disturb antitumor immunity by suppressing the activities of effector T cells." (PMID 30619765, 2018). "Additionally, CD4+ T cells participation is important in tumor control, as CD4+ Tregs are associated with tumor progression, whereas CD4+ Th1 with an antitumor immune response." (PMID 29755647, 2018). "Supporting this, we demonstrated that loss of MIF expression in the primary tumor led to an increased abundance of intra-tumoral IFNgamma-producing CD4+ and CD8+ T cells, and that depletion of T cells from mice bearing MIF-deficient tumors restored growth to the level of MIF-expressing tumors." (PMID 29864117, 2018). "Furthermore, young, but not elderly, IL-2/CD40-treated mice demonstrated additional reductions in other regulatory markers expressed by tumor-associated CD4+ T cells, including ICOS and IL-10." (PMID 30560130, 2018). "Furthermore, the TNFR2 antagonist preferentially suppressed the activity of tumor-associated CD4+ Treg cells, but had little inhibitory effects on peripheral CD4+ Treg cells or cells from healthy donors." (PMID 29623079, 2018). "The effectiveness of Th1 cells in the generation and maintenance of strong immunological memory has been shown, as well as association between secretion of IFNγ by CD4 T cells and their anti-tumor effects, e.g. by reducing proliferation and angiogenesis and enhancing apoptosis of tumor cells." (PMID 28183282, 2017). "DC-based anticancer vaccines could potentially deliver tumour-associated antigens to lymphoid tissues and induce the activation of antigen-specific CD4+ and CD8+ T cells that can home to neoplastic lesions and mediate tumour regression." (PMID 28276533, 2017). "Therefore, MHC-II expression in tumor cells and its close association with CD4-positive T cells in our study suggests the possible cytotoxic activity of CD4-positive T cells on MHC-II expression in TNBC cells." (PMID 28817603, 2017).
tumor (continued). "Furthermore, PD1 expression on CD4+ cells was associated with both increased tumour size and advanced clinical stage." (PMID 28146145, 2017). "In addition, optimal tumor control and rejection in the combination Vax/aCD122 therapy was associated with reduction of both suppressive CD4+ Tregs and G-MDSCs in the TME." (PMID 29312597, 2017). "Unfortunately, interpretation of the result obtained with the CD4‐deficient mice is problematic, since the CD4+ T‐cell population not only includes Tregs, but also other types of T cells that may induce an immune response against the tumor cells." (PMID 27932444, 2017). "Tumour-associated B-cells induce and regulate T-cell immune responses through antigen presentation and CD4+ T-cell activation, contributing to the differentiation of CD4+ T-cells and polarisation of Th1 and Th2 subsets." (PMID 28817839, 2017). "Thus, CD4 T cell subsets and their associated cytokines can have profound effects on tumor progression." (PMID 27832300, 2017). "The increased CTL activities are prevented by CD8 monoclonal antibodies, and partly abrogated by CD4 or NK monoclonal antibodies, indicating its killing activity against tumor may be associated with the activation of CD4+T, CD8+ T and NK cells." (PMID 28915590, 2017). "These CD8+ Treg cells could induce the death of CD4+ T cell which is also a hallmark of their suppressive property similar to the CD8+ Treg cells isolated from tumor patients." (PMID 28487507, 2017). "Thus depression of CD4+CD25+FoxP3+ numbers was associated with the capacity to control tumours in the gastrointestinal tract of T. muris infected mice." (PMID 28650985, 2017). "B cells can also facilitate expansion of CD8 and CD4 T cells specific for tumor-associated antigens, thanks to their ability to present (through MHC class II) or cross-present (through MHC class I) epitopes independent of their B-cell receptor (BCR) specificity." (PMID 26883106, 2016). "The enhanced anti-tumor effect of α-CD137/α-PD-1 mAbs when combined with radiotherapy was associated with accumulation (>60-fold) of intratumoral CD4+ and CD8+ T cells with an effector phenotype, which contributed to the therapeutic effect of this radio-immunotherapy approach." (PMID 27160390, 2016). "However, CD4+ T cells that are generated through exposure to tumor-associated antigens via antigen presentation on MHC class II are tumor-specific and play a more direct role in the tumor microenvironment." (PMID 27576783, 2016). "Our data are also supporting the notion that preexisting AE36 immunity might be beneficial through induction of antigen specific CD4+ T cells, with cytotoxic function, that could successfully recognize tumor cells with down-regulated HLA class I alleles." (PMID 27891225, 2016). "Epithelial cell adhesion molecule-positive (EpCAM+) CTCs are a proven independent risk factor for HCC recurrence in our previous study, while immune suppressive CD4+CD25+ regulatory T cells (Treg) intra-nuclear expressing Foxp3+ are associated with tumor immune tolerance and immune escape." (PMID 27439521, 2016). "IDH-1-mutated tumor patients display either increased or decreased CD4-positive lymphocytes." (PMID 27585656, 2016). "Secondly, as CD4+ T cells play an anti-tumor role by enhancing cellular immune responses, insufficient generation of CD4+ T cells could cause an inability of the host to reject the tumor." (PMID 27270307, 2016). "The results demonstrated that Tim‐3 on CD4+ T cells was positively associated with tumor stage." (PMID 27516959, 2016). "Third, could tumor antigen-specific CD4 T cells, or innate cells such as NK cells or myeloid cells, be targeted to promote anti-tumor immunity in tumors harboring B2M mutations?" (PMID 27782862, 2016). "Similarly, tumor-associated IFN-γ-expressing CD4+ (Th1) cells were significantly increased in WT and IL10−/− B16/F10 mice after anti-TGF-β injection." (PMID 27075020, 2016).
tumor (continued). "High tumour grade was shown to be significantly associated with tumour infiltration (intratumoural, stromal) by CD4+ and CD8+ T cells and stromal FOXP3+ T cells, which may have contributed to the NAC-induced pCR." (PMID 27777963, 2016). "Furthermore, our results are partly in line with previous studies that showed that tumor infiltration by higher numbers both of CD4+T-cells and CD8+T-cells was associated with longer survival of PDAC patients." (PMID 25669968, 2015). "In a phase I/II trial in patients with metastatic melanoma, direct intra-dermal injection of mRNA coding for relevant tumor-associated antigens was well tolerated and influenced the frequency of vaccine-antigen directed CD4 and CD8 T cells as well as regulatory T cells (T Regs)." (PMID 26082837, 2015). "Because CD4+ T cells play a pivotal role in the growth of sporadic CRC, we next determined whether the diminished tumor incidence and severity in IL-21-deficient mice was associated with reduced infiltration and/or function of colonic CD4+ cells." (PMID 25839161, 2015). "Furthermore, the loss of CD28 expression in naïve CD4+ T cells induced by tumor cells was significantly alleviated when they were separated in the Transwell system." (PMID 25231413, 2014). "The data presented above suggested that secretion of PGE2 and TGF-β by the Sa-3 tumor cell after treatment with erlotinib might be the cause of the decreased CD4+ T cell responses." (PMID 25240937, 2014). "In this study, the mortality rate was significantly high in patients with associated comorbidity, HIV positivity, CD4+ count <200 cells/μl, high histological grade and advanced stage of the tumor, presence of metastases at the time of diagnosis, and associated complications." (PMID 25085449, 2014). "In addition, the GITR-GITRL interaction has been known to attenuate Treg cell function via the loss of Foxp3 expression as well as enhance tumor-specific effector CD4+ and CD8+ T cell functions." (PMID 25105508, 2014). "HNSCC patients are characterized by systemic immunosuppression, exhibiting increased populations of regulatory T cells and CD34+ progenitor cells, which suppress CD8+ T cell- and CD4+ helper T cell-mediated immunity at the primary tumor site and are associated with a poorer prognosis." (PMID 24698959, 2014). "The overall mortality rate was 46.5% and it was significantly associated with comorbidity, HIV positivity, CD4+ count <200 cells/μl, high histological grade, advanced stage of the tumor, presence of distant metastases at the time of diagnosis, and associated complications (P < 0.001)." (PMID 25085449, 2014). "Several effector mechanisms have been implicated for tumor-specific cytotoxic CD4+ T cells." (PMID 24782871, 2014). "After 4 days of co-culture of splenocytes with DC lines, we observed a CD8+ T cell response that was markedly higher in splenocytes from the C57BL/6, CD4-depleted, and FasL-deficient mice than in splenocytes from the tumor-bearing CD8β-depleted, Pfn-deficient, and CD11c:SV40LgT hosts." (PMID 25101081, 2014). "This would have produced TNP-modified X5563 tumor antigens that could have been recognized and processed by the hapten-specific B-cells causing further cross-activation and the formation of CD4+ T-cells specific for X5563 cells." (PMID 24949488, 2014). "In contrast, in CD4+ T cell-deficient mice, there was only a 34%–42% inhibition of tumor growth." (PMID 25196596, 2014). "Likewise to FoxP3, tumor cell associated expression of L1CAM has been shown to confer immunosuppressive functions to CD4+ T cells in vitro (unpublished observations)." (PMID 24797069, 2014). "These analyses showed that in both tumor microenvironments, IL-10 treatment caused a significant increase of CD4+granzyme+ T cells with a concomitant decrease of CD4+CD25+FoxP3+ Treg, reminiscent of what observed after vaccination with gp10025-33 peptide-pulsed DC." (PMID 23663506, 2013).
tumor (continued). "Ipilimumab may also rescue tumor-impaired IFN-γ pathways in CD4+ T cells, since a number of genes associated with IFN-γ signals such as STAT1, ISG15, GBp1, and EIF2AK2 were up-regulated by ipilimumab (data not shown)." (PMID 22788688, 2012). "In addition, we examined the effect of GalNAc glycosylation of a physiological tumor associated MUC1 glycopeptide known to induce CD4+ and CD8+ T cell responses." (PMID 23189185, 2012). "Besides targeting tumor cells, CD4+ effector T cells have been implicated in inhibiting tumor angiogenesis by acting on tumor stroma via IFNγ." (PMID 22400040, 2012). "The reason that TIM-3 is highly expressed in FOXP3+CD4+ TILs might be due to constant stimulation by tumor associated antigens within the tumor site." (PMID 22363469, 2012). "On the other hand, CD4+ T lymphocytes may promote tumor cell invasion and metastasis by altering the function of tumor-associated macrophages (TAMs)." (PMID 21732475, 2011). "Although one patient whose tumor had S127F mutation showed weak CD4+ T cell responses against both mutated and corresponding wild-type peptides, no significant mutation-specific CD4+ T cell response could be detected (data not shown)." (PMID 21858191, 2011). "Moreover, blocking IL-13 prevented the rapid tumor growth associated with the addition of the CD4+ T cells to the model, suggesting that in this model CD4+ T cells are polarized to produce IL-13 and promote tumor development." (PMID 21281484, 2011). "Thus, analysis of the TCR repertoires of activated and Treg cells in various anatomic locations shows that both tumor neo-antigen and natural B16-associated antigens shape the repertoires of CD4+ T cell subsets." (PMID 21049016, 2010). "Interestingly, MHC I deficient mice showed a better degree of protection than MHC II deficient mice, implying a CD4+ T cell-dependent CD8+ T cell-independent mechanism of tumor protection." (PMID 20844763, 2010). "To determine the origin of Treg cells in cancer, we used an experimental model in which immune response, of both effector and Treg cells, to tumor-associated antigens can be characterized in mice with a restricted and readily characterized CD4+ T cell repertoire." (PMID 21049016, 2010). "However, recently, adoptive cell transfer of CD8+ T cells contaminated with CD4+ T cells into lymphodepleting tumour-patients caused a great inhibition of tumour growth." (PMID 19277034, 2009). "Since CD4+ T cells play critical roles in cell-mediated immunity, detail knowledge of the effect tumor-derived PGE2 might have on CD4+ T cell survival and the underlying mechanism may, therefore, help to overcome the overall immune deviation in cancer." (PMID 19812686, 2009). "In addition, Th17 cells have been associated with effective tumor immunity in a model of adoptive transfer of TCR transgenic CD4+ T cells specific for the shared self-tumor antigen tyrosinase-related protein 1 (TRP1)." (PMID 19457253, 2009). "Tumour CD4+ T lymphocytes were also positively associated with CD8+ T lymphocytes (P<0.001)." (PMID 18797461, 2008). "These vaccines are engineered to encode tumor-associated antigens (TAAs) or patient-specific neoantigens, allowing host antigen-presenting cells to translate the mRNA and present immunogenic epitopes that stimulate robust CD4+ and CD8+ T cell responses against tumor cells." (PMID 41601966, 2026). "High-risk scores are positively correlated with pro-tumor immune components (M0/M2 macrophages, activated mast cells, and neutrophils), while negatively associated with anti-tumor immune elements (activated DCs, M1 macrophages, resting mast cells, and memory CD4+/CD8+ T cells)." (PMID 40721869, 2025). "In addition, the number of immune cells with antitumor ability dropped sharply in the high-risk group, specifically CD8+ and CD4+ T cells, which can recognize and kill tumor cells and can also produce various cytokines and chemokines to guide other immune cells to attack tumors." (PMID 41343099, 2025).